ENSG00000251967
Gene: Small nucleolar RNA gene on chromosome 3 (46,650,510 to 46,650,590, forward strand). Ensembl gene ENSG00000251967.
Homologues: Orthologues: zebrafish snord80.2 (35% identical), zebrafish snord80.1 (33% identical). Paralogues in human: SNORD77B (51% identical).